FUT4 (fucosyltransferase 4)
Description:
[Isoform Short]: Catalyzes alpha(1->3) linkage of fucosyl moiety transferred from GDP-beta-L-fucose to N-acetyl glucosamine (GlcNAc) within type 2 lactosamine (LacNAc, Gal-beta(1->4)GlcNAc) glycan attached to N- or O-linked glycoproteins. Robustly fucosylates nonsialylated distal LacNAc unit of the polylactosamine chain to form Lewis X antigen (CD15), a glycan determinant known to mediate important cellular functions in development and immunity. Fucosylates with lower efficiency sialylated LacNAc acceptors to form sialyl Lewis X and 6-sulfo sialyl Lewis X determinants that serve as recognition epitopes for C-type lectins. Together with FUT7 contributes to SELE, SELL and SELP selectin ligand biosynthesis and selectin-dependent lymphocyte homing, leukocyte migration and blood leukocyte homeostasis (By similarity). In a cell type specific manner, may also fucosylate the internal LacNAc unit of the polylactosamine chain to form VIM-2 antigen that serves as recognition epitope for SELE. [Isoform Long]: Does not generate Lewis X antigens.
Synonyms: Fuc-TIV; ELFT; FCT3A; CD15; FUTIV; LeX; SSEA-1
Tractability: Small molecule: a high-quality ligand is known. Antibody: UniProt predicts a signal peptide or a membrane-spanning region. PROTAC: its protein half-life has been measured; a small molecule that binds it is known.
Target class: Enzyme; Transferase
Gene: Protein-coding gene on chromosome 11 (94,543,921 to 94,549,895, forward strand). Ensembl gene ENSG00000196371.
Subcellular location: Golgi apparatus, Golgi stack membrane
Subcellular location (Human Protein Atlas): Vesicles
Pathways (Reactome):
Metabolism: Lewis blood group biosynthesis
Gene Ontology:
Molecular function: 4-galactosyl-N-acetylglucosaminide 3-alpha-L-fucosyltransferase activity; alpha-(1->3)-fucosyltransferase activity; fucosyltransferase activity
Biological process: oligosaccharide metabolic process; regulation of leukocyte cell-cell adhesion; carbohydrate metabolic process; glycoprotein biosynthetic process; L-fucose catabolic process; lymphocyte migration into lymph node; oligosaccharide biosynthetic process; positive regulation of leukocyte tethering or rolling; positive regulation of neutrophil migration; sphingolipid metabolic process
Cellular component: trans-Golgi network; Golgi apparatus; Golgi membrane; membrane; cell periphery; cell surface; Golgi cisterna membrane
Genetic constraint (gnomAD): Loss-of-function variants: 5 observed, 8.63 expected, observed/expected ratio (o/e) 0.58, 90% interval 0.3 to 1.22. That is too few expected variants to judge how well the gene tolerates losing a copy. Missense variants: 880 observed, 677.7 expected, observed/expected ratio (o/e) 1.3, 90% interval 1.23 to 1.37. Synonymous variants: 417 observed, 311.22 expected, observed/expected ratio (o/e) 1.34, 90% interval 1.24 to 1.45.
Homologues: Orthologues: chimpanzee FUT4 (99% identical), guinea pig FUT4 (73% identical), rat Fut4 (64% identical), mouse Fut4 (61% identical), rabbit FUT4 (60% identical), pig FUT4 (55% identical), dog FUT4 (52% identical), tropical clawed frog fut4 (35% identical), Caenorhabditis elegans fut-1 (19% identical), Caenorhabditis elegans fut-3 (16% identical), Drosophila melanogaster FucTD (16% identical), Caenorhabditis elegans fut-4 (16% identical), and 9 more. Paralogues in human: FUT7 (30% identical), FUT5 (30% identical), FUT3 (29% identical), FUT6 (29% identical), FUT9 (26% identical), POFUT4 (17% identical), POFUT3 (16% identical).
Diseases named in the same sentence as FUT4 in open-access papers:
FUT4 is named in the same sentence as 231 diseases in open-access papers, as found by Europe PMC text mining. Sharing a sentence is not in itself a finding about the gene and the disease. The quoted sentences say what the papers report.
breast cancer (54 papers, 2007 to 2025). A primary or metastatic malignant neoplasm involving the breast. "Since induction of FUT4 expression is also correlated with expression of another cancer-associated marker, the cancer antigen 15.3 (CA15.3), FUT4 has been proposed as a novel biomarker for the early prognosis of breast cancer." (PMID 29527514, 2018). "The level of miR-200b, as well as its oncogenic target, FUT4, in the serum are novel and specific diagnostic markers for breast cancer and are potential targets for breast cancer therapy." (PMID 28692034, 2017). "Additionally, in breast cancer, FUT4 and its associated glycans exert a cancer-promoting activity, which is limited by miR-224-3p, miR-200b/c and miR-493-5p, which is sponged by lncRNA GAS6-AS2." (PMID 36555445, 2022). "Similarly, Fucosyltransferase IV (FUT4), associated with the proliferation and metastasis, is proposed as an effective biomarker for breast cancer diagnosis." (PMID 33193605, 2020). "Finally, elevated expression levels of FUT4 in breast cancer cells are associated with the acquisition of a mesenchymal phenotype and a greater cell motility." (PMID 29527514, 2018). "Moreover, we collected serum samples from healthy women, breast cancer patients and those receiving regular chemotherapy to further analyze alterations in miR-200b and FUT4 by real-time PCR and enzyme-linked immunosorbent assay." (PMID 28692034, 2017). "miR-200b and FUT4 are potential diagnostic and therapeutic targets for breast cancer." (PMID 28692034, 2017). "For example, FUT4 is involved in the metastasis and proliferation of breast cancer cells and can be used as a potential biomarker for the diagnosis and prognosis of breast cancer." (PMID 38807207, 2024). "For instance, FUT4 regulated epithelial mesenchymal transition of breast cancer cells via activation of PI3K/Akt and NF-κB signaling pathways." (PMID 37946130, 2023). "The miR-26a-b/MALAT1 axis already described for FUT4 regulation in colorectal cancer also modulates ST8SIA4 in breast cancer cell lines." (PMID 36555445, 2022). "We examined a handful of CSC markers commonly associated with breast cancer (ALDH1A1, ABCG2, PGP, FUT4)." (PMID 34579762, 2021). "Previous studies reported that miR-224-3p promotes breast cancer development by targeting FUT4, promotes cervical cancer by repressing FIP200-mediated autophagy, and participates in the recurrence of human osteosarcoma." (PMID 33425890, 2020). "Fucosyltransferase 4 (FUT4)-catalyzed fucosylated N-glycans were dramatically increased in multidrug-resistant breast cancer cells." (PMID 31022917, 2019). "In breast cancer cells, increased FUT4, 5, 6, 10 and 11 levels correlate with increased migration and proliferation and the increased expression of angiogenesis-related genes including VEGFA, VEGFR1, VEGFR2, and FGF2." (PMID 31450600, 2019). "Recently, FUT4 expression was shown to be regulated by several miRNAs, which are downregulated in breast cancer tissues, highlighting one mechanism by which FUT4 fucosylation is enhanced in breast cancer tissues." (PMID 31450600, 2019). "Compared to the sensitive T47D cells, the drug-resistant breast cancer cell line T47D/ADR overexpresses the FUT4 enzyme." (PMID 29527514, 2018). "In conclusion, this study highlights a new strategy for gene therapy and diagnosis of breast cancer through a new network miR-200b/FUT4." (PMID 28692034, 2017). "In contrast, FUT4 siRNA co-transfected with Anti-miR-200b or FUT4 siRNA transfected alone in breast cancer cells significantly decreased the proliferation rate." (PMID 28692034, 2017). "Further, the levels of miR-200b and FUT4 in the serum were recovered after chemotherapy, compared with those in untreated breast cancer patients." (PMID 28692034, 2017).
breast cancer (continued). "In the current study, we detected alterations of the levels of miR-200b and FUT4 in tissues, as well as in the serum of breast cancer patients, and found that the level of miR-200b is negatively correlated with FUT4 expression in breast cancer patients." (PMID 28692034, 2017). "We observed that miR-200b was lower, whereas FUT4 were higher both in mRNA and protein levels in breast cancer than that in adjacent tissues." (PMID 28692034, 2017). "Our results provide new information for serum diagnosis using miR-200b and FUT4 as key markers and therapeutic targets for breast cancer." (PMID 28692034, 2017). "The results revealed a significant suppression of FUT4 expression after transfection with miR-200b mimics, as well as decreased proliferation ability and invasion capability of breast cancer cells both in vitro and in vivo." (PMID 28692034, 2017). "The results showed that, in the serum of breast cancer patients, miR-200b level was low, whereas FUT4 level was relatively high compared with that in controls, showing a negative correlation coefficient (r=−0.7581)." (PMID 28692034, 2017). "We found that miR-200b level was decreased, whereas that of FUT4 was increased in tissues and serum of breast cancer compared with that in the control by real-time PCR, western blotting and enzyme-linked immunosorbent assay." (PMID 28692034, 2017). "Using two different breast cancer cell lines, the authors established that miR-224-3p, through the downregulation of the FUT4 gene, is capable of reverting the MDR phenotype and of increasing sensitivity to taxol, vincristine, and doxorubicin." (PMID 27446804, 2016). "For example, in breast cancer, FUT4 transcription is regulated by HSF1 and Sp1 to inhibit cell proliferation; in HaCaT cells, FUT4 level is lower due to the higher methylation of CpG island in FUT4 promoter." (PMID 26094873, 2015). "FUT4 has been proposed as an effective diagnosis biomarker of breast cancer." (PMID 33892787, 2021). "The miR-493-5p/FUT4 pathway has therapeutic potential in breast cancer." (PMID 32850310, 2020). "FUT4 (fucosyltransferase 4) is reported as a biomarker for the diagnosis of breast cancer." (PMID 31487856, 2019). "In addition, expression of FUT4, whose synthetic epitopes are Lewisx, Lewisy, and sialyl Lewisx, is higher in breast cancer tissues and serums compared to normal tissues and control serums, respectively." (PMID 29527514, 2018). "Similarly, induction of FUT4 expression in the breast cancer cell line A431 leads to increased cell cycle progression and skews the balance toward the S-phase of the cell division process." (PMID 29527514, 2018). "Recent studies and our previous work revealed that FUT4/LeY was highly expressed in a variety of solid tumors including breast cancer, ovarian cancer, pancreatic cancer, colon cancer, melanoma and NSCLC and was associated with invasion, metastasis, and poor prognosis." (PMID 28423676, 2017). "In conclusion, the study highlights that FUT4 could apply as a novel target for miR-200b that suppress the proliferation and metastasis of breast cancer cells by reducing α1,3-fucosylation and LeY biosynthesis of glycoproteins." (PMID 28692034, 2017). "To explore whether miR-200b exerts its function by regulating FUT4 expression, we prevented the expression of FUT4 in breast cancer cells of MCF-7 and MDA-MB-231 by miR-200b mimics transfection." (PMID 28692034, 2017). "Next miR-200b and FUT4 levels were evaluated in the tissues and serum samples of breast cancer." (PMID 28692034, 2017). "Additionally, miR-200b and miR-200c could suppress migration and invasion of breast cancer cells by regulating ezrin-radixin-moesin and fucosyltransferase-4." (PMID 31488193, 2019). "Therefore, using clinical samples, breast cancer cells and breast cancer xenograft mouse model, we confirmed that FUT4 could serve as a new target gene for miR-200b." (PMID 28692034, 2017).
breast cancer (continued). "Therefore, we hypothesized that inhibiting FUT4 was a potential strategy for inhibiting breast cancer development." (PMID 28692034, 2017). "FUT8 promotes breast cancer cell invasiveness by remodeling TGF-β receptor core fucosylation and FUT4 is an effective biomarker for the diagnosis of breast cancer." (PMID 30619732, 2018). "The results also showed that miR-200b suppressed FUT4 expression and inhibited tumor growth and metastasis in MCF-7 and MDA-MB-231 breast cancer cells, as well as in the xenografted tumor tissues and metastatic lung tissues." (PMID 28692034, 2017). "In our previous study at our laboratory, it was shown that FUT4 and its regulated LeY sugar chains were significantly up-regulated in NSCLC and breast cancer and promoted EMT induction through EGFR and PI3K/Akt-GSK3β activation." (PMID 28423676, 2017). "Similarly, FUT4 has been proposed as a marker for breast cancer, and expression of FUT8 is positively correlated with migration and invasiveness of breast cancer cells and lung cancer." (PMID 40642090, 2025).
glioma (54 papers, 2010 to 2025). A benign or malignant brain and spinal cord tumor that arises from glial cells (astrocytes, oligodendrocytes, ependymal cells). "The Spearman correlation analysis results suggested that the immune marker sets of Treg (FOXP3, CCR8, TGFβ1), TAM (CCL2, CD68, IL-10), and MDSC (CD33, ITGAM, FUT4) were significantly associated with the PROS1 expression in glioma." (PMID 36685506, 2022). "In vivo and in vitro investigations indicated that circ-PARP4, as a miRNA sponge, directly interacted with miR-125a-5p, which then controlled FUT4 to produce the oncogenic influence on glioma behavior." (PMID 35883576, 2022). "ZBTB42 is positively related to glioma stem cells marker genes such as CD44, MSI1, Fut4, and NES and the high expression group has a stronger relationship with glioma stemness." (PMID 36762114, 2023). "Two fucosyltransferases (FUT4 and 7) responsible for CD15 and CD15s synthesis were modulated in four human cancer cell lines (three lung cancer and one glioma)." (PMID 31104223, 2019).
lung carcinoma (41 papers, 2013 to 2025). "As reported, FUT4 has been linked to programmed cell death protein 1 (PD-1)-related immunosuppression, which leads to poorer prognosis in patients with operable lung cancer." (PMID 35251014, 2022). "According to earlier studies, FUT4 may prevent cisplatin resistance in lung cancer from being caused by FOXO1-induced apoptosis." (PMID 38343056, 2024). "Within the purview of lung carcinoma, both FUT4 and its synthesized cancer-specific glycoantigen, Lewis Y (LeY), are aberrantly elevated, with FUT4 demonstrating notable overexpression within lung carcinogenic tissues." (PMID 37818195, 2023). "Our findings were parallel to the findings of previous studies where MALAT1 promoted drug resistance in cancer cells via modulating STAT3 activation in lung cancer and enhanced FUT4 fucosylation by sponging miR-26a/26b involving PI3K/AKT pathway." (PMID 35281907, 2022). "Current study suggests these two SLs to be the promising agents for overcoming paclitaxel resistance in A549 lung cancer cells via MALAT1/STAT3/FUT4 axis." (PMID 35281907, 2022). "In this study, we explored the positive correlation of MALAT1 with STAT3 and FUT4 activity in paclitaxel resistant A549 (A549/T) lung cancer cells." (PMID 35281907, 2022). "An EMT-promoting activity of FUT4 was confirmed by studies in lung cancer cells and in breast cancer." (PMID 34356834, 2021). "FUT4 overexpression promotes lung cancer invasion, migration, epithelial-mesenchymal transition (EMT), and cell adhesion." (PMID 34948129, 2021). "FUT4 is frequently upregulated in lung cancer, and FUT4 knockdown increases chemosensitivity to cisplatin by suppressing FOXO1-induced apoptosis." (PMID 34948129, 2021). "In contrast, FUT4 overexpression in lung cancer cells has been reported to suppress the EGFR signaling pathway and attenuate EGFR-mediated invasion of tumor cells." (PMID 32486143, 2020). "Our study also indicates that down-regulation of FUT4 by Rg3 is correlated to the EMT in lung cancer cells." (PMID 26636541, 2016). "On the one hand, ginsenoside Rg3 inhibits lung cancer migration and invasion by down-regulating fucosyltransferase IV (FUT4)-mediated EGFR inactivation and blocking MAPK and NF-κB signaling pathways." (PMID 27655708, 2016). "We collected paraffin sections to examine FUT4 and N-cadherin protein expression, the results showed FUT4 and N-cadherin were more highly expressed in lung cancer than normal lung tissues, and they had the same tendency." (PMID 26636541, 2016). "In conclusion, Rg3 inhibits EMT and invasion of lung cancer by down-regulating FUT4 mediated EGFR inactivation and blocking MAPK and NF-κB signal pathways." (PMID 26636541, 2016). "The further study showed that down-regulating FUT4 increased E-cadherin, and decreased Snail, N-cadherin and Vimentin in lung cancer cells, and thus, hindering EMT." (PMID 26636541, 2016). "To further investigate the mechanism of Rg3 in lung cancer, we detected the expression of FUT4 in the lung cancer tissues, and the inhibitory effect of Rg3 on FUT4 in vitro and in vivo." (PMID 26636541, 2016). "The positive FUT4 expression rate was 11.4 % (4/35) in normal lung tissues, and 60.9 % (39/56) in lung cancer tissues (P < 0.001)." (PMID 26636541, 2016). "We used Western blot to analyze FUT4 and N-cadherin protein expression in fresh lung cancer tissues." (PMID 26636541, 2016). "GS-Rg3 inhibited epithelial-mesenchymal transition (EMT) and invasion of lung cancer by down-regulating fucosyltransferase 4 (FUT4) mediated EGFR inactivation and blocking MAPK and NF-κB signal pathways." (PMID 28119606, 2016). "We found that FUT4 was highly expressed in lung cancer tissues compared with the normal lung tissues, and Rg3 significantly down-regulated FUT4 expression in a dose- and time-dependent manner." (PMID 26636541, 2016).